HES1 (hes family bHLH transcription factor 1)
Diseases named in the same sentence as HES1 in open-access papers (continued):
Sharing a sentence is not in itself a finding about the gene and the disease.
cancer (152 papers, 2009 to 2026). A tumor composed of atypical neoplastic, often pleomorphic cells that invade other tissues. "Aberrant activation of the Notch-Hes1 axis is strongly associated with malignant phenotypes across various cancers, particularly in enhancing cellular proliferation, invasion, and metastatic capacity." (PMID 40755759, 2025). "This inhibition is broadly linked to cancer progression and metastasis due to its promotion of the upregulation and expression of the downstream target, HES1." (PMID 41488655, 2025). "This implies that miR-182-mediated blocking of HES1 expression is responsible for the activation of metastatic traits in RET oncogene-dependent cancers, since loss of this transcription factor leads to a higher invasive potential of the cells." (PMID 28122586, 2017). "Overexpression of Hes1 has been associated with the development of pancreatic, breast and ovarian cancers and its down-regulation results in accelerated differentiation and decreased cellular proliferation in several cancer models." (PMID 26650241, 2015). "WFA has been reported to inhibit Notch1 and downstream signaling genes (Hes1 and Hey1) that have been implicated in cancer initiation and progression." (PMID 25264898, 2014). "Dysregulation of Notch signalling has been implicated in various inflammatory diseases and cancers, suggesting that HES1 may play a role in the inflammatory processes associated with UC." (PMID 40362323, 2025). "Long thought as a marker of normal colon stem cells, HES1 expression has recently been associated with promoting stemness in a subset of the colonic epithelial cells, in addition to being proposed as a regulator of cancer stem cells in the colon." (PMID 39684467, 2024). "Furthermore, the synergistic effect observed when combining Hes1-deficiency with PD-1 blockade warrants further investigation for the development of improved cancer treatment strategies." (PMID 39702544, 2024). "HES1 is positively correlated with the levels of stem cell markers, suggesting that it may play a critical role in tumorigenesis through increasing the number of stem cell like cancer cells (CSCs) associated with mesenchymal phenotypes." (PMID 31683806, 2019). "Overall, EGCG can directly or indirectly inhibit aberrant Notch activation and downregulate core components such as Notch1 and Hes1, ultimately suppressing cancer progression." (PMID 41602823, 2026). "It reduces NICD production by inhibiting γ-secretase activity, downregulates Hes1/Hey1, and induces cancer cell apoptosis while suppressing proliferation/migration." (PMID 41602823, 2026). "Stabilized Notch2 activates downstream signaling components such as C-Myc, Cyclin D3, and HES1, which drive cancer cell survival and chemoresistance." (PMID 40393971, 2025). "The role and prognostic value of Hes1 in different cancers remain controversial, and its specific functions and regulatory mechanisms still require further investigation to ensure the effectiveness of targeting strategies." (PMID 40755759, 2025). "Elucidating the underlying molecular mechanisms for HES1 and HES4 repression requires the interrogation of the epigenetic information of both TPCS‐like and less malignant cancer cells." (PMID 39731353, 2025). "Increased expression of HES1 contributes to cancer cell survival, EMT, and stemness, which are key factors in drug resistance mechanisms." (PMID 40507238, 2025). "Notch inhibition via DAPT reduces β-catenin levels, whereas Wnt inhibition with ICG-001 increases Hes1 expression, indicating the existence of a compensatory balance mechanism that ensures cancer cell survival." (PMID 40755759, 2025). "The expression and activity of Hes1 in cancer are primarily regulated by the evolutionarily conserved canonical Notch pathway, and are also influenced by oncogenes, epigenetics, the microenvironment, and various other signaling pathways." (PMID 40755759, 2025).
cancer (continued). "Recent studies have widely investigated the potential of targeting Hes1 and inhibiting its expression as a cancer therapeutic strategy, although its precise mechanisms of action are not yet fully elucidated." (PMID 40755759, 2025). "Although dual-targeting strategies show promise, mechanistic variations in Hes1’s pathway regulation across cancer types demand further exploration." (PMID 40755759, 2025). "Hes1 expression patterns, clinicopathological characteristics, and prognostic significance across malignant tumors." (PMID 40755759, 2025). "The treatment with CB dramatically decreases the activity of the Notch promoter at its IC50 by reducing the expression of the Notch-targeted genes Hes1 and Hey1 in both cancer cells." (PMID 38563878, 2024). "This study unveils a novel mechanism by which Notch signaling regulates TAM function and highlights HES1 as a promising therapeutic target for overcoming T cell suppression and potentiating cancer immunotherapy." (PMID 39702544, 2024). "Hes1 have an important function in the maintenance of cancer stem cells self-renewal, cancer metastasis, and epithelial-mesenchymal transition (EMT) process induction, as well as chemotherapy resistance." (PMID 39469631, 2024). "Recent studies have shown that HES1, which is a helix–loop–helix transcription factor, performs important functions related to stemness, metastasis, and drug resistance in cancer." (PMID 37190139, 2023). "In cancer research, HES1 has been reported to play crucial roles in the maintenance of cancer stem cell self-renewal, induction of the EMT process, cancer metastasis, and antagonism of drug-induced apoptosis." (PMID 37190139, 2023). "As a downstream target gene of NOTCH signaling pathway, the role of HES1 in cancer has been extensively studied." (PMID 37046345, 2023). "Pathologically, HES1 is highly expressed in various cancers, such as pancreatic cancer, CRC, and non-small cell lung cancer, which are associated with poor outcomes." (PMID 37957183, 2023). "HES1 has been reported to be overexpressed in multiple somatic tumors and its dysregulated expression led to the occurrence and development of cancer." (PMID 37957183, 2023). "Among these genes, we discovered and confirmed one putative target gene, namely HES1, that plays a role in the regulation of pathways in cancers." (PMID 37190139, 2023). "Recent studies have shown that HES1, which is a helix–loop–helix transcription factor, performs important functions in stemness, metastasis, and drug resistance in cancer." (PMID 37190139, 2023). "Several studies have demonstrated that HES1 is involved in the regulation of various biological processes in cancers, such as cell stem maintenance, proliferation, and metastasis." (PMID 37957183, 2023). "NICD levels and Notch target genes, including Hey1, Hes1, and cyclin D1 (Ccnd1), were significantly upregulated in HG-treated Met1 cancer cells, suggesting that HG activates Notch signaling." (PMID 36707514, 2023). "HES1 has been reported to maintain stem cell state in several cancers and also reported to be expressed in murine and human placenta." (PMID 36574992, 2023). "DMRTA2 has been found to regulate the expression of Hes1 gene, and this gene has been studied to have roles in cancer stem cell (CSC) maintenance, metastasis, and drug-induced apoptosis antagonism." (PMID 34976314, 2022). "HES1 plays a critical role development of cancer stem cells (CSCs), cancer metastasis, and multidrug resistance in many cancers." (PMID 36497496, 2022). "TLE5 overexpression inhibited Notch signaling activation through recruitment of TLE1 and HDAC3, converting active Notch transcriptional complexes into repressive complexes, which reduced the expression of Notch target genes such as HES1 in clone cancer cells." (PMID 36438567, 2022).
cancer (continued). "Mechanistically, it was demonstrated that RASSF1A stabilizes the E3 ligase RNF4, which targets HES1 for proteasome-dependent degradation, thus preventing the expression of HES1-dependent proliferation and cancer stemness genes." (PMID 35954292, 2022). "HES1 has been involved in several cancer developments by its role in transcriptional activation or inhibition." (PMID 33390847, 2021). "JAGGED1 is a notch ligand and plays a key role in cancer stem cells; HES1 is a downstream molecule of JAGGED1." (PMID 34725550, 2021). "HES1 has been involved in promoting cancer cell transformation and increasing chemoresistance by an enhancement in the STAT3 transcriptional activity 47-49." (PMID 33390847, 2021). "JAGGED1 is the Notch ligand and plays key roles in cancer stem cell differentiation and metastasis; HES1 is a downstream molecule of JAGGED1." (PMID 34725550, 2021). "HES1 has been also identified as a potential driver of anti-cancer drug resistance, in addition to upregulation of cancer cell proliferation and migration." (PMID 34830951, 2021). "We also identified potential transcriptional factors with known oncogenic roles in HCC, e.g. ZEB1, or in other cancer types, e.g. HES1, NR6A1, PATZ1, PAX4 and MTF1, in GE1-HCC." (PMID 33541355, 2021). "HHEX caused a repression of a series of neural stemness genes or/and genes promoting cancer, Sox1, Sox2, Myc, Cdh2, Vim, Hes1, Zic1, Pax6, Ezh2, and Lsd1." (PMID 34595169, 2021). "Hes1 is a transcriptional repressor that inhibits the differentiation of cancer cells, playing an essential role in the pathogenesis of cancers." (PMID 32974175, 2020). "Overall, our study demonstrated the role of the JMJD2C/HIF1α/HES1 signaling axis in the miR-216b-mediated enhancement of the anti-cancer effects of cisplatin." (PMID 32972441, 2020). "HES1 participates in cellular differentiation, cell apoptosis and cell self-renewal, and the expression level of HES1 is frequently abnormal in cancer cells." (PMID 29665790, 2018). "Recent studies suggest an important role for HES1 in the regulation of normal and cancer stem cells." (PMID 29652830, 2018). "HES1 is a basic helix-loop-helix transcription factor, which regulates Notch signaling proteins that are central in development and cancer." (PMID 30418981, 2018). "To explore the effects of HES1 on cancer further, we knocked down HES1 via siRNA transfection for 48 h and then quantified the numbers of apoptotic cells via Annexin V and PI staining and flow cytometric analysis." (PMID 29665790, 2018). "Many studies indicate that HES1 has the potential to induce cancer stem cells with self-transforming ability and to trigger apoptosis resistance and oncogenesis progression." (PMID 29665790, 2018). "According to these findings, it was concluded that HES1 induces stem-like cell self-renewal and increases the number of cancer stem cells in colorectal cancer." (PMID 29652830, 2018). "Hierarchical Cluster data suggests a much more complex situation of NOTCH1 and HES1 expression correlated with cancer stem cell marker CD44, ALDH1, Slug and SOX2." (PMID 27108536, 2016). "Previous reports have showed that Bmi-1 promotes drug resistance and cellular invasion in cancer cells and cancer stem cells, moreover, Hes1 is a well known key apoptosis-inhibiting genes." (PMID 26452029, 2015). "The four genes (HES1, PRKCH, ELF5 and TM4SF1) validated above have all been associated with cancer progression." (PMID 26356672, 2015). "Western blotting and immunofluorescence showed that ablation of Bmi-1 expression restored the Hes1-induced EMT phenomenon in cancer cells." (PMID 26452029, 2015). "Increasing evidence supports that Hes1 regulates cancer cell proliferation, differentiation, senescence and resistance to chemotherapy." (PMID 26452025, 2015). "Expression of HES1 and HEY1 was rather enhanced in cancer tissues, reaching significance for HES1, whereas HES5 was unchanged." (PMID 25167871, 2014).
cancer (continued). "Across the cancer tissues, expression of HES1 mRNA was significantly increased compared to normal bladder, despite the significant downregulation of NOTCH1, NOTCH2 and DLL1." (PMID 25167871, 2014). "Notch1 signaling is increased in a variety of cancers and activates downstream target genes, including HES1, HES5, DTX1, NRARP, and c-MYC." (PMID 20161710, 2010). "Here, we sought to establish whether HES1 oscillations may regulate ER+ cancer cell quiescence and reactivation." (PMID 41770916, 2026). "Emerging evidence highlights Hes1 as a multifunctional modulator of this pathway across cancers." (PMID 40755759, 2025). "Molecular mechanisms and functional roles of Hes1 in malignant tumors." (PMID 40755759, 2025). "The relative expression levels of PIK3CA, AKT, PTEN, VEGFA, NOTCH1, and HES1, as the key cellular signaling pathways involved in cancer biology, angiogenesis, and cell survival/proliferation, were investigated to determine the effects of SCC, DOK, and HaCaT products on fibroblasts." (PMID 40729037, 2025). "However, increasing evidence demonstrates that Hes1 is aberrantly expressed in many human malignancies Hes1 can serve as a potential prognostic biomarker for cancer and is expected to become a significant target in the field of cancer therapy." (PMID 40755759, 2025). "In summary, targeting Hes1 demonstrates significant potential in cancer therapy." (PMID 40755759, 2025). "CTNNB1 and FBXW7 genes are some of the most altered Wnt pathway genes in OC, while in the Notch pathway the receptors (NOTCH1-4), ligands (such as DLL1, JAG2), as well as the canonical target (HES1), are some of the most dysregulated Notch genes in cancers overall." (PMID 40002854, 2025). "Notably, dysregulation of the Notch-Hes1 axis sustains cancer progression by inhibiting differentiation and promoting cancer stem cell proliferation." (PMID 41210254, 2025). "Targeting HES1 in TAMs appears to be a promising strategy for cancer immunotherapy." (PMID 39702544, 2024). "HES1 is recognized for its role in promoting self-renewal across various cancer cell types." (PMID 39702544, 2024). "Our previous study and other studies have indicated that HRY/Hes1 enhances cancer cell stemness." (PMID 37219449, 2023). "Hes1 is a known transcriptional repressor that plays pleiotropic roles in various aspects of cellular regulation including stem cell maintenance in several cancer cells." (PMID 36574992, 2023). "It is known that function of HES1 in cancer might be abrogated, and high HES1 expression might be associated with less differentiated tumors." (PMID 36980177, 2023). "However, KCNQ1OT1 and HES1 have higher expression in the carcinoma tissue compared with normal tissues." (PMID 36944972, 2023). "Notably, HCC cells with strong expression levels of Hes1 were predominantly observed in area #1, and some of these Hes1-expressing cancer cells were stained positive for the cell proliferation marker Ki67." (PMID 35064244, 2022). "In addition, I-BET151 impeded BRD4 binding to the NOTCH1 promoter, diminishing the expression of Hes1 and cancer-cell renewal activity." (PMID 35215234, 2022). "Metformin may target cancers through HES1 signaling; however, much surrounding this potential mechanism of action still requires further study." (PMID 36672573, 2022). "The activation of NOTCH1 is, in fact, able to induce HES1 and to start cancer progression." (PMID 33672900, 2021). "However, as previously shown, HES1 allows cancer cells to evade differentiation and irreversible cell cycle arrest, indicating an active role of HES1 in the carcinogenic process." (PMID 34383828, 2021). "Highlighting the controversial consequences of pro-survival pathways modulation after Notch signaling inhibition, the combination of GSI RO4929097 with oxaliplatin abrogated drug-induced apoptosis and improved survival of cancer cells, which was even more sustained by HES1 silencing." (PMID 34680255, 2021).
cancer (continued). "Moreover, the protein expression of Hes1 progressively decreased over time, which is consistent with Hes1-induced inhibition of cancer cell differentiation." (PMID 32974175, 2020). "Furthermore, HES1 has been reported to be highly-active in OS, with studies suggesting that HES1 promotes the critical phenomenon of chemotherapy resistance in cancer." (PMID 32972441, 2020). "The expression of miR‐524 can restrain the proliferation of cancer cell via targeting and inhibiting the expression of Smad2, Hes1, and Tead1 which are essential proteins for transforming growth factor‐β (TGF‐β), Norch, and Hippo signaling pathways, respectively." (PMID 30643726, 2019). "Hes1 and Hey1, known as direct downstream targets of Notch, belong to an extensive family of basic helix-loop-helix (bHLH) proteins and play a critical role in the regulation of cell cycle and apoptosis in various cancers." (PMID 30606241, 2019). "HES1 has been proposed as an indicator of Notch signaling activity in many cancers." (PMID 27888801, 2017). "Targeting the Notch-Hes1 pathway could be exploited for therapeutic purposes in Notch activated cancers." (PMID 26650241, 2015). "Results of these studies and the present study suggest that Hes1 overexpression is a common feature in human cancers and the expression of Hes1 may be served as a helpful prognostic marker to evaluate the prognosis of NPC patients." (PMID 26452025, 2015). "HES1 was highly expressed in these cancer cells under normal culture conditions." (PMID 20010940, 2010). "Additionally, Hes1 is an important factor in the development of other tissues as well as different cancer types so investigations of the differences between Hes1 interactions in these different tissues could be of interest as well." (PMID 40379916, 2025). "Therefore, HES1 could exhibit distinct roles depending on the cancer type, tissue context or genetic background." (PMID 41009728, 2025). "HES1 had a complex relationship with various pathways, which had the potential to trigger cellular metamorphosis and enhance its invasive capabilities, while also playing a significant role in the differentiation, proliferation, and immune suppression of cancer cells." (PMID 39691708, 2024). "Additionally, Notch1/Hes1 signaling pathway participates in EMT of cancer cells." (PMID 38166853, 2024). "Thus, PTBP3 overexpression may upregulate Id1a expression and downregulate Id1b expression to attenuate the inhibition of Hes1 activity, which indirectly increases the activity of Hes1, leading to the inhibition of cancer cell differentiation." (PMID 32974175, 2020). "Moreover, since HES-1 lies at the crossroads of multiple signaling pathways, the co-inhibition of these pathways through targeting HES-1 might represent a new strategy for cancer therapy." (PMID 32974155, 2020). "To further investigate the target signaling pathways involved in the inhibition of cancer stemness by physciosporin, we performed reporter assays in HEK293T cells transfected with plasmids encoding gene-conjugated firefly luciferase: TOPFLASH-luc, Gli-luc, Hes1-luc, and CSL-luc." (PMID 31795147, 2019). "Notch pathway negatively impacts the activity of the Wnt pathway in most cancers; Wnt can also impact the expression of DLL1, HES1 and NOTCH2 on the protein level, while β-catenin can also interact with NOTCH1 and reduce its ubiquitination." (PMID 40002854, 2025). "Here, we investigate the role of HES1, a downstream target of Notch signaling, in TAM-mediated immunosuppression and explore its potential as a target for cancer immunotherapy." (PMID 39702544, 2024). "We also examined the Notch1/Hes1 signaling pathway, which is known to participate in the EMT of cancer cells." (PMID 38166853, 2024). "Downregulation of ST6GAL1 decreases Jagged1, DLL-1, Notch1, Hes1, Hey1, MMPs and VEGF, and suppresses cancer cell proliferation, migration and invasion." (PMID 37256139, 2023).